GSTP1 (glutathione S-transferase pi 1)
Diseases named in the same sentence as GSTP1 in open-access papers (continued):
Sharing a sentence is not in itself a finding about the gene and the disease.
cancer (continued). "Out of the major classes of GSTs, GSTP1 has significance in the diagnosis of cancer because it is expressed abundantly in tumor cells." (PMID 23077566, 2012). "In the present study, it was also demonstrated that hypermethylation of GSTP1 occurs more frequently in advanced stage cancer cases than in early disease status cases." (PMID 23226781, 2012). "Out of the single gene perturbations, activation of glutathione S-transferase P (GSTP1) gene was by far the most effective in blocking the cancer phenotype." (PMID 20184733, 2010). "Hypermethylation of EPB41L3 and GSTP1 was compared in 93 cancer tissues by methylation-specific PCR." (PMID 20860828, 2010). "The best characterized of these events, GSTP1 promoter methylation, occurs in >90% of cancers and 70% of precursor high grade prostatic intraepithelial neoplasia (PIN) lesions and can also be detected in blood and urine samples." (PMID 19283074, 2009). "Our findings now for the first time suggest a possible relationship between the GSTP1 genotype and irinotecan efficacy in cancer patients." (PMID 18797455, 2008). "Taken together, studies in both bacteriae and cancer patients indicate that GSTP1-GG protects its carriers against platinum-induced toxicities." (PMID 18162130, 2007). "In our data set, optimal separation between carcinoma and normal tissues was achieved by GSTP1 and RARB2 hypermethylation, identifying >80% tumour samples correctly." (PMID 15292941, 2004). "Here, using a sensitive MS-PCR method, we found 70% of carcinoma tissues from a Central European population to display GSTP1 hypermethylation with rare methylation in adjacent normal tissues, supporting its value as a marker." (PMID 15292941, 2004). "The analysis of the carcinomas of cluster 5 shows that only three of the six investigated resistance proteins were up-regulated (GSTP1, MGMT, MVP/LRP)." (PMID 12177790, 2002). "In addition to GSTP1 inhibition, targeting telomerase presents another approach to limit cancer cell proliferation." (PMID 39954068, 2025). "This downregulation may contribute to demethylation of the GSTP1 promoter, reactivation of its expression, and inhibition of cancer cell growth." (PMID 41226811, 2025). "This detailed interaction profile highlights the dimer’s superiority over the monomer, suggesting that dimerization could be a promising strategy for developing more potent GSTP1 inhibitors, especially for applications targeting chemoresistant cancers." (PMID 39954068, 2025). "Elevated levels of GSTP1 expression are found in many human cancers." (PMID 40649927, 2025). "Several studies reported that GSTP1 overexpression enhances cancer cell proliferation, invasion, and formation of metastatic nodules, while suppression of the enzyme has the opposite effect, which suggests GSTP1 acts as a positive regulator of metastatic processes." (PMID 40014124, 2025). "For alcohol consumption, 12 articles (4238 cases and 5394 controls) were about the association between GSTM1 and cancers, 8 articles (2949 cases and 4025 controls) were about GSTT1 and cancers and 5 articles (1898 cases and 2527 controls) were about GSTP1 and cancer among drinkers." (PMID 38579033, 2024). "Finally, two genes that are widely overexpressed in drug-resistant cancers, the glutathione S-transferase Pi 1 (GSTP1) and ABCG2, a member of the ATP-binding cassette family, were also found in this cluster." (PMID 38999963, 2024). "In several types of cancer, the GSTP1 gene is affected by hypermethylation." (PMID 39125992, 2024). "GSTP1 polymorphism (AG + GG/AA) was not statistically associated with the overall cancer risks in either smokers or nonsmokers." (PMID 38579033, 2024). "Cancer cells expressing GSTP1 Val105 exhibit greater tolerance to ethacrynic acid-induced toxicity." (PMID 39125992, 2024).
cancer (continued). "Notably, SMURF2’s ability to promote ferroptotic cell death through GSTP1 degradation offers an alternative pathway to overcome apoptosis resistance, expanding therapeutic options for refractory cancers." (PMID 39697237, 2024). "Expression of GSTs, especially GSTP1-1, is increased in cancer." (PMID 39125992, 2024). "In pan-cancer analysis using TCGA cohorts (Dataset EV7), we observed associations between LF6 and DNA methylation (P = 4.3 × 10−68), RNA levels (P = 6.2 × 10−28) of GSTP1 as well as INFG response (P = 4.0 × 10−161) across different tumour types." (PMID 39592856, 2024). "Therefore, pro-oxidant cancer drugs dramatically increase intracellular ROS and thus, induce oxidative stress by interfering with ROS homeostatic regulators such as glutathione S-transferase pi 1 (GSTP1)." (PMID 39435263, 2024). "SMURF2 promotes ferroptosis in cancer cells by mediating the degradation of GSTP1." (PMID 39697237, 2024). "Investigation into CIPN association with polymorphisms in GSTM1, GSTT1 and GSTP1, identified no significant results in a mixed cancer cohort." (PMID 36939926, 2023). "There are many physiological roles for GSTP1: It breaks down a variety of carcinogenic substances, detoxifies and eliminates potentially genotoxic foreign complexes, and defends cells from DNA deterioration and cancer development." (PMID 37901797, 2023). "The GSTP1 gene is hypermethylated in a number of cancer types." (PMID 37901797, 2023). "Early research on the GST family showed that the GSTP1 gene is crucial for a number of physiological functions, such as catalysis and deoxylation of electrophilic chemicals, the control of oxidative stress, cell signaling, and the development of cancer." (PMID 37901797, 2023). "Importantly, we tested the GSTP1 specific pharmacologic inhibitor ezatiostat on freshly raised cancer organoids and induced crizotinib‐resistant organoids bearing ALK fusion proteins." (PMID 36709476, 2023). "Evidences from genetic manipulation studies show GSTP1 facilitates cell viability and increases resistance to cisplatin and targeted therapy including gefitinib, erlotinib, or afatinib for the relevant EGFR mutated, and crizotinib for ALK translocated cancers." (PMID 36709476, 2023). "Expression of GSTP1 in cancer cells correlated with resistance to chemotherapy." (PMID 36428575, 2022). "Many GSTs, e.g., GSTO1, GSTP1, GSTK1, GSTA4 and GSTM3, are reported to cause resistance in cancer." (PMID 36428646, 2022). "These emerging pieces of evidence suggest that the efficacy of chemotherapy and the overall outcome in cancer patients could be significantly improved if used in combination with GSTP1 inhibitors." (PMID 33946704, 2021). "GSTP1 inhibitors may, thus, be useful for treating some forms of cancer, as well as for reversing resistance." (PMID 34299488, 2021). "In a subset of cases, however, some or all cancer cells stained positively for GSTP1." (PMID 34191807, 2021). "Interestingly, we found that the increase in GSTP1-positive cancers in Black men was greater in ERG-positive cases." (PMID 34191807, 2021). "GSTP1 protein staining in cancer cells in Black and White patients." (PMID 34191807, 2021). "Thus, the increased frequency of GSTP1-positive cancers in Black versus White men occurred in low and intermediate grade and stage cancers only." (PMID 34191807, 2021). "Interestingly, we also found that GSTP1-positive carcinomas were often heterogeneous for GSTP1 protein (41%)." (PMID 34191807, 2021). "The ethacrynic acid (a strong diuretic drug) is conjugated to 2-amino-2-deoxy-D-glucose to reduce diuretic effects but maintaining the inhibitory capacity against GSTP1-1, the ethacrynic acid derivatives are molecules with promising anti-proliferative activities against cancer cells." (PMID 31357662, 2019).
cancer (continued). "These various outcomes could also be attenuated by silencing of glutathione S-transferase P1 (GSTP1), a mediator of metabolic alterations and drug resistance in various cancers, and a regulator of cysteine oxidation." (PMID 30890751, 2019). "GSTP1 methylation in the first and the second negative biopsy was associated with the risk of cancer detection in the final sampling, while no clear association was found for the other genes." (PMID 31666119, 2019). "The epigenetic control of GSTP1 gene results relevant in cancer prevention and diagnosis." (PMID 31357662, 2019). "Therefore, the association of GSTP1/ GSTM1 variants with highly malignant disease and poor prognosis in cancer patients was suggested." (PMID 31646988, 2019). "Another category of compounds in cancer research is the inhibitors of GSTP1-1." (PMID 31357662, 2019). "Also, an interindividual variability of GSTP1 expression in the normal samples and among patients with the same stage or grade of cancer was observed." (PMID 30043549, 2018). "Deregulated expression of GSTP1 protein and aberrant promoter methylation of GSTP1 gene were reported in various human tumors and were shown to be involved in the molecular pathway for cancer development." (PMID 30043549, 2018). "Additionally, it shows activities against cancer cells through disrupting the interaction between the GSTP1-1 and key signaling effectors, which are crucial factors for apoptosis and cell cycle." (PMID 29358310, 2018). "We suggest that GSTs expression (GSTM3 or GSTP1) could be involved in modulating detoxification processes in cancer cells, and therefore, may participate in the survival response to conventional chemotherapy in patients." (PMID 29774096, 2018). "Therefore, our data suggest that a fluorogenic probe targeting GSTP1-1 for molecular imaging would also be very useful for the early diagnosis and/or evaluation of chemopreventive agents for these types of cancers." (PMID 28747791, 2017). "Genetic polymorphisms within distinct haplotypes prevalent in certain breeds can affect GSTP1 expression and carcinogen detoxification, and thus may be useful as genetic markers for cancer in dogs." (PMID 29046813, 2017). "We investigated the GSTP1 gene methylation status using methylation specific PCR (MS-PCR) and assessed methylation correlation with gene silencing through immunohistochemistry (IHC) in cancer and healthy paraffin embedded tissues obtained from prostatectomy." (PMID 27594734, 2016). "We thus confirmed that GSTP1 methylation is a cancer specific biomarker and we enforced the concept that GSTP1 could be an early diagnostic marker." (PMID 27594734, 2016). "GSTP1 is the most widely distributed member of the glutathione S-transferase (GST) family that catalyzes intracellular detoxification of various electrophiles and plays critical roles in susceptibility to many diseases including cancer." (PMID 27149165, 2016). "The well-known cancer-specific hypermethylation of GSTP1 was also present, validating our analyses." (PMID 27014907, 2016). "Hypermethylation of the GSTP1 promoter has also been previously reported as having association with prognostic values, and repression of PALLD gene has been shown to contribute to invasive motility and cancer cell migration." (PMID 28155687, 2016). "The present review discusses applications of epigenetic alterations affecting GSTP1 in cancer medicine used alone or in combination with other biomarkers for cancer detection and diagnosis as well as for future targeted preventive and therapeutic interventions including by dietary agents." (PMID 25076909, 2014). "A second example shows the analysis of the hypermethylation of the GSTP1 promoter in cancer." (PMID 24271385, 2014). "Hence Ezatiostat acts as a Glutathione S-Transferase P1-1 inhibitor and activates the pro apoptotic Jun kinase in cancer cells that express GSTP1-1." (PMID 23841999, 2013).
cancer (continued). "In patients receiving docetaxel for the treatment of cancer, the occurrence of grade ≥2 CIPN was more frequent in individuals homozygous for GSTP1105Ile allele, that encodes glutathione S-transferase pi 1 (GSTP1), an enzyme involved in the regulation of oxidative stress." (PMID 24385965, 2013). "The enzyme GSTP1-1 (GSTP- Glutathione S Transferase pi1) can bind and inhibit the Jun Kinases with subsequent impact on growth and differentiation of healthy hematopoietic stem cells and cancer cells." (PMID 23841999, 2013). "In plasma samples, promoter hypermethylation of GSTP1 gene was significantly correlated with higher age (≥50), hypermethylation of P16 gene was correlated with pathologic early stage of cancer and hypermethylation of BMP6 gene was correlated with lymph node involvement (P<0.05)." (PMID 21283676, 2011). "For these reasons, GSTP1 appears to be crucial for cell survival and inhibition of apoptosis, and is considered to be important for the survival of transformed clones and for cancer drug resistance." (PMID 19826491, 2009). "Upon further investigation of GSTP1 methylation in the same 20 cancer specimens, however, we could detect methylation in 80% of cases using MSP (data not shown)." (PMID 19283074, 2009). "Interestingly, most of the highly up regulated and down regulated (top 10) genes have already been reported to have roles in cancer or other cellular activities related to cancer, such as GSTP1, HIF-1, and SGK." (PMID 18560586, 2008). "Altered DNA methylation, related to the fundamental role of epigenetic events in cancer now constitutes a growing field of clinical investigation in cancer and could possibly explain variable levels of GSTP1 expression in our patients." (PMID 16434992, 2006). "In addition to GSTP1, the activity of GSTM1 and GSTT1 may be partly implicated in the response to platinum-based cancer treatment and the detoxification of platinum compounds." (PMID 39903276, 2025). "All these findings suggest that GSTP1 overexpression, beyond its role in drug resistance, may contribute to the metastatic ability of cancers including promoting EMT, modulating MMPs, and upregulating certain signaling pathways, thus becoming an attractive target for metastasis research." (PMID 40014124, 2025). "The increased level of GSH synthesis and expression of GSTP1 in most types of cancer cells, along with a reversed pH gradient (i.e., a lower extracellular pH of ~6.7–7.1 and a higher intracellular pH of 7.4), may influence the rate of S-glutathionylation in the tumors." (PMID 39125992, 2024). "Phenotype scanning revealed that seven out of the thirteen identified proteins (KDELC2, GSTP1, CTSS, CPNE1, ISLR2, SFTPB, and ICAM5) were associated with other traits, but none of these traits were likely to bias the associations between identified proteins and cancers." (PMID 37735436, 2023). "Therefore, in this review we focus on GSTP1, which could be a potential effective regulator in radiotherapy of cancer in GST family." (PMID 36589232, 2022). "Therefore, GAPDH, GSTP1 and other proteins reported here may represent candidate targets to further enhance the potential for nitroimidazole-based cancer therapeutics." (PMID 33640700, 2021). "Cases with any or all TMA cores with cancer cells staining positive for GSTP1 occurred across all Gleason grade groups and stages, and the higher percentage of cases from Black patients positive for GSTP1 was apparent among all grade groups except in grade group 5 and except in stage group 3." (PMID 34191807, 2021). "Since NQO1 and GSTP1 are phase-II detoxification enzymes that reduce quinones directly to hydroquinones, eliminating the formation of ROS produced by redox cycling, the combination of inhibition of NQO1 and GSTP1 may offer a potential solution for cancer therapy." (PMID 33087132, 2020).
cancer (continued). "The methylation levels of GSTP1 in the negative biopsies were associated with the risk of cancer diagnosis in the last sampling: the OR per 1% increase in methylation level was 1.14 (95% CI 1.01–1.29), and 1.21 (95% CI 1.07–1.37), for the highest methylation level." (PMID 31666119, 2019). "In conclusion, all studies about GSTP1-1 and cancer could be divided into two groups." (PMID 31357662, 2019). "However, variant GSTP1 expression did not significantly correlate with the progression or malignant behavior of cancer (p > 0.05)." (PMID 30043549, 2018). "Thus, GSTP1’s inhibition on cancer progression may be accomplished by arresting the cell cycle at the G1/S transition in HCC cells." (PMID 29507666, 2018). "Whether GSTP1 and CLDNs playing significant roles in different biological characteristics of cancers is not clear, we hypothesize that there may be a close correlation in activity/function between CLDNs and GSTP1, which may provide a possible direction for cancer chemotherapy." (PMID 29116019, 2017). "Secondly, GSTP1 functions as a caretaker gene with its loss resulting in increased oxidative DNA damage and mutagenesis, thus, in BRCA2 deficient cancers already sensitive to oxidative stress, any loss of GSTP1 may have a more pronounced effect and be integral in tumour development." (PMID 28893223, 2017). "However, while hypermethylation-based cancer field effects have been demonstrated for GSTP1 in several previous studies of PC24, 25, 26, 27, 28, 29, the existence of such epigenetic field effects remains to be investigated for our eight novel candidate methylation marker genes." (PMID 28084441, 2017). "The GSTP1 gene, which encodes the pi-class glutathione S-transferase, is a defense against oxidative damage to the genome and is expressed in high levels by epithelial cells in proliferative inflammatory Atrophy (PIA), which are considered to be precursors of premalign and malign prostate lesions." (PMID 26064423, 2015). "We speculate the possibility that PL inhibits GSTP1 or CBR1 activity and caused ROS accumulation, which in turn oxidized intracellular thiol-containing antioxidant agents like GSH and Trx, thus sensitized the cancer cells to AF-induced apoptosis." (PMID 26431378, 2015). "Although some methylated markers such as RASSF1A and GSTP1 have potential as prognostic indicators individually, 'methylation signature' panels could be much more informative and accurate for monitoring cancer progression." (PMID 22443985, 2012). "Our data suggest that HCC-related DNA methylation does occur, although to a lesser extent in the adjacent non-HCC tissues, suggesting that methylation of the 5′ region of the GSTP1 promoter could be part of the cancer microenvironment that cultivates the development of HCC." (PMID 22536438, 2012). "It was reported that the metabolic action of GST enzymes may differ by cancer site; the highest concentrations of GSTP1 have been observed in oral and pharyngeal tissues, and the highest concentrations of GSTM1 have been observed in laryngeal tissue, relative to the other GSTs." (PMID 23144854, 2012). "Indeed, we have recently reported that dienone cyPG, like 15d-PGJ2 and Δ12-PGJ2 induce cross-linking of the P1-1 isoform of glutathione S-transferase (GST), which is involved in cancer chemoresistance, through a mechanism likely involving cysteine residues present in different GSTP1-1 monomers." (PMID 21253588, 2011). "Furthermore, because GSTP1 hypermethylation correlated strongly with that of three other genes, their hypermethylation may also occur at early stages of cancer development." (PMID 15292941, 2004). "The differential expression of DDAH1 and PDIA6 in GSTP1 knockdown PDAC cells is particularly intriguing, as both are involved in redox homeostasis and are frequently upregulated in various cancers." (PMID 40719618, 2025).